TNF (tumor necrosis factor)
Diseases named in the same sentence as TNF in open-access papers (continued):
Sharing a sentence is not in itself a finding about the gene and the disease.
tumor (continued). "The authors suggested that targeting predominant cytokines like TNFα in the TME would be more useful in combination with conventional chemotherapy regimens or treatments that target malignant cells directly, and better tolerated as well, than simply addressing tumor cells with targeted therapy." (PMID 33540543, 2021). "This 45-nucleotide long aptamer could recognize both murine and human PDL1 and modulate the tumor microenvironment by elevated CD4+ and CD8+ T cell infiltration and IL2, IFNγ, TNFα and other chemokine expression at the tumor site, which might form a loop against tumor proliferation." (PMID 34575825, 2021). "The study aimed at assessing whether curcumin induces apoptosis of RCC and the involvement of AKT/mTOR pathway, the effects of curcumin on pro-inflammatory TNF-a, IL6 and IL-8 cytokines, and finally, to understand the role of curcumin in autophagy and tumor-growth in vivo." (PMID 34402718, 2021). "The exact role of TNF-α in tumor development is not entirely clear." (PMID 33668730, 2021). "Interestingly, increased doses of the antibody did not enhance TNF-α-mediated but increased TRAIL anti-tumor activity, especially in UPCI-SCC-90 cells." (PMID 33737574, 2021). "Moreover, in an in vitro co-culture system, knockdown of PRMT5 in tumor cells could directly enhance the expression of IFN-γ, TNF-α and granzyme B in T cells." (PMID 34522232, 2021). "Furthermore, we provide experimental evidence that these nanoparticles can be used as carriers for delivering TNF to tumors and to induce more efficient anti-tumor effects than nanoparticles lacking the isoDGR targeting moiety." (PMID 34124009, 2021). "Furthermore, we performed flow cytometric experiments to detect some parameters (NK1-1, CD107a, CD69, tumor necrosis factor (TNF)-α, and interferon (IFN)-γ) on NK cells in tumors to investigated the state about tumor-infiltrating NK (TINK) activation, with the fresh tumor tissue from mouse." (PMID 34471091, 2021). "In the absence of TNF-α signaling, tumor immune surveillance is severely abrogated." (PMID 34199989, 2021). "Loss of USP22 expression delays TNFα/carbobenzoxyvalyl‐alanyl‐aspartyl‐[O‐methyl]‐fluoromethylketone (zVAD.fmk)/Smac mimetic‐induced necroptosis in several human tumor cells, without affecting TNFα‐induced nuclear factor‐kappa B (NF‐κB) signaling or TNFα‐mediated extrinsic apoptosis." (PMID 33369872, 2021). "Additionally, tumor hypoxia with resulting acidosis is known to abrogate the function of surrounding immune cells via the induction of anti-immunogenic mediators (e.g., IL-1b, IL-8, IL-6, TNFα, and TGF-b) contributing to tumor cell escape of immunogenic control." (PMID 34831136, 2021). "Since cIAP1 is well known to act downstream of the TNF/TNFRs pathway and TNF is a known cytokine involved in permeability, we examined whether TNF and TNFRs levels are influenced upon tumor challenge in the absence of cIAP1." (PMID 33546280, 2021). "Therefore, EGCG impaired tumor growth in a murine model of breast cancer by both decreasing TAM tumor infiltration and repolarizing M2-like to M1-like macrophages, as evidenced by the diminished IL-6 and TGF-β and increased TNF-α levels." (PMID 33572626, 2021). "Notably, the iso1-mediated targeting mechanism increased the anti-tumor activity of TNF without increasing its toxicity, as judged from the even lower loss of body weight caused by 1-Au/TNF compared to 2-Au/TNF." (PMID 34124009, 2021). "Additionally, it can increase CD8+ T cell infiltration in tumors, normalize tumor vessels, and induce the production of cytokines such as IFN-γ, TNF-α, and MIG, which may inhibit tumor metastasis." (PMID 34367975, 2021). "Furthermore, to examine the frequencies of tumor-infiltrating WT1-specific CD4+ T cells, intratumoral CD4+ T cells from WT1 peptide vaccine-treated mice were stimulated with WT135–52 helper peptide and their IFN-γ and TNF-α production was measured." (PMID 34355173, 2021).
tumor (continued). "The activated MSCs robustly support tumor progression and metastasis directly by inducing EMT, and indirectly through the production of numerous immunomodulatory molecules, such as TGFβ, PGE2, IL6, IL8, VEGF, TNFα, IL1β, IDO, and FSTL1, to generate and expand Tregs, MDSCs, and DCregs." (PMID 33535613, 2021). "A murine model of breast cancer showed that tumor exosome induction of IL-6 expression can block bone marrow DC differentiation, and that pancreatic cancer-derived exosomes can regulate the expression of TLR4 and cytokines, such as TNFα and IL-12 expression in DCs through miR-203." (PMID 33671415, 2021). "Factors that can promote the anti-tumor neutrophil phenotype include chemokines (e.g., CXCL2, CXCL5, CXCL8, CCL2, CCL3, CCL5, CXCL12 (SDF-1), CXCL16 and IL-8) alone or together with G-CSF/GM-CSF, TNFα, IFNβ, IFNγ, IFNγ together with TNFα, Resolvin D1, hepatocyte growth factor (HGF) and IL-17." (PMID 34572138, 2021). "In addition, NK depleted tumours have reduced IFN-γ and TNF-α expressing T cells." (PMID 34888493, 2021). "L19-TNF (Fibromun, Philogen S.p.A., Siena, Italy) is a fully-human immunomodulatory product consisting of a non-covalent homotrimeric immunocytokine featuring human TNF fused to the L19 antibody (specific to EDB of fibronectin, a marker of tumor neovasculature)." (PMID 34576184, 2021). "These genes were defined as the tumor reactive signature (TRS), including co-inhibitory receptors (CTLA4, PDCD1, TIGIT and HAVCR2), reactive markers (CD38 and ENTPD1), effector molecules (NKG7 and PRF1), tumor necrosis factor TNFRSF9 and critical exhaustion-related regulator TOX." (PMID 34804045, 2021). "Moreover, the studies of tumor microenviroment have shown that the homing ability of stem cells is established on the basis of special signals of lesions, such as TNF-α, TGF-β and other cytokines secreted in tumor microenvironment, as well as soluble factors secreted by tumors." (PMID 34069607, 2021). "Chemokines like TNFα, IL-1, HGF, IFN-α, and their receptors activate MAPK, nuclear factor-kappa-β (NF-kB), and phosphatidylinositol-3 kinase (PI3K)/Akt, signal transducer and activator of transcription (STAT) pathways involved in cell proliferation, survival, invasion, metastasis, and tumor growth." (PMID 33925575, 2021). "Interestingly, we observed that although the serum levels of several cytokines including IL‐6, TNF‐α, and IL‐1β (but not IL‐1α) increased in C26‐tumor‐bearing mice, these effects were prevented by treatment with GW (Fig EV3, EV4D–G)." (PMID 34096686, 2021). "Increased secretion of IL-6, TNFα, CCL2, CCL5, CXCL9 and GM-CSF, which are pro-inflammatory factors combined with decreased secretion of anti-inflammatory factors including IL-4, IL-28A, CCL24, CXCL12 and SCF from infected HEL299 fibroblasts, is expected to be tumor-promoting and enhance metastasis." (PMID 34575976, 2021). "When we dissected tumor tissues to examine TILs 14 days after therapy, intratumoral CD8+ T cells were proportionally increased only in the combination group; B16F10 tumors under the combinatory therapy contained the most CD8+ T cells producing effector cytokines IFN-γ and TNF-α." (PMID 34615877, 2021). "The M1 macrophages produce pro-inflammatory factors (TNF-α, IL-1β, and iNOS), chemokines (CXCL10, CXCL11, and CCL2), antigen-presenting molecules such as MHCII, costimulatory molecules (CD86 and CD80), and antigen-treated peptidases, which play an anti-tumor role in cancer." (PMID 34034714, 2021). "Moreover, the genes associated with T cell function (e.g., perforin and IFN-γ) and T cell recruitment (e.g., CCL5) were enriched within the tumor and the level of IFN-γ and TNF-α in plasma after treatments was elevated, especially following the combined treatment." (PMID 34307367, 2021). "Therefore, we screened for a syngeneic tumor cell line, which did not die in response to Smac mimetics and TNF using viability stains and flow cytometry." (PMID 33546280, 2021).
tumor (continued). "Given the increase in production of IL‐1β, TNF‐α, IL‐12, IL‐22, and IL‐6 by the expanded inflammatory Ly6C+MHCII+ monocyte population in the tumor following the administration of SL7207, it was hypothesized that monocyte populations may underpin the tumor‐growth inhibition effects of SL7207." (PMID 34633664, 2021). "TNF-α is produced by activated monocytes/macrophages, that promote cell proliferation and differentiation and also synergize with epi-epidermal growth factor and insulin to promote the expression of the EGF receptor and produce growth factor-like effects on some tumor cells." (PMID 33494759, 2021). "To verify whether the expression of TNFRSF9, TNF, and IFNG could identify all TILs actively engaged in tumor recognition in situ, we re-analyzed multiple scRNAseq datasets using fresh tumor biopsies and applied the activation gene sets as a proxy of presumed ongoing antigen stimulation in the TME." (PMID 34707600, 2021). "Indeed, the blocking of TNFα has been suggested to boost the response to the immune checkpoint blockade, by enhancing tumor regression and preventing activation-induced CD8 T cell death in MC38 and B16-OVA mouse tumor models." (PMID 34073253, 2021). "Therefore, TNF-α and TGF-β play a mutually promoting role in the regulation of fibrosis and EMT, and they complement each other and are two essential factors in the process of tumor formation." (PMID 35069596, 2021). "Tryptanthrin effectively inhibited tumor growth in 4 T1 murine breast cancer model; modulated expression levels of nitric oxide synthase 1 (NOS1), COX-2, and nuclear factor kappa-B (NF-κB) in mouse tumor tissues; and regulated some factors such as IL-2, IL-10, and TNF-α in mice." (PMID 37789475, 2021). "Furthermore, in studies reported by our laboratory and others as well, it has already been shown that the proinflammatory cytokine TNF-β promotes tumor progression and thus activates CRC cells malignancy (HCT116 cells and HCT116 5-FU resistant cells) with the same efficacy as TNF-α." (PMID 34660256, 2021). "Besides, IL-2 level in HT treated tumor displayed a slight increase, while the concentrations of TNF-α and IL-10 showed no obvious changes as compared to control group." (PMID 33986437, 2021). "Additionally, TNFα is known to be a major inducer of chemokines such as CCL2 and IL-6 in the TME, thus increasing monocyte and macrophage infiltration as well as tumor growth and angiogenesis, respectively." (PMID 33540543, 2021). "The DEGs enriched in TAMs were related to pathways such as extracellular matrix disassembly, response to hypoxia, positive regulation of cholesterol efflux and response to TNF and IL1B, implying that they may promote cell migration, angiogenesis, tumor progression and inflammation." (PMID 33144684, 2021). "CD8 T cells, as the primary anti-tumor cells in tumor infiltrating lymphocytes, could realize the releasing of perforin and granule enzyme B via Fas / FasL pathway through cell contact, or destroy targeted cells via the release of IFN—γ and TNF cytokines." (PMID 34544391, 2021). "Finally, we confirm the importance of MyD88 in macrophages showing that BCG induces the release of inflammatory cytokines (TNF-α, IL-6, IL-1β) and nitric oxide by WT macrophages in co-culture with infected tumor cells, but not in MyD88−/− BMDMs." (PMID 34341449, 2021). "However, certain cytokines, such as tumor necrosis factor-α (TNF-α), and interleukin-6 (IL-6), can be also induced by tumor cells as well as non-cancerous cell types, such as epithelial cells or cancer-associated fibroblasts (CAFs)." (PMID 34557865, 2021). "Although, the C-7 bispecific VHH and cetuximab triggered a similar release pattern of TNF and cytotoxic molecules by NK cells, the use of a CD16 specific VHH provides several advantages compared to ADCC mediated through binding of the Fc domain of a therapeutic tumor-targeting antibody to CD16." (PMID 34771609, 2021).
tumor (continued). "Furthermore, HCC patients showed a decrease in proinflammatory cytokines, such as tumor necrosis factor-α (TNF-α), interferon-γ (IFN-γ), interleukin (IL)-1, and an increase in immunosuppressive cytokines (IL-4, IL-5, IL-8, and IL-10) in the tumor microenvironment, resulting in a poor prognosis." (PMID 34830949, 2021). "Moreover, M2 macrophage also releases cytokines and chemokines, such as IL-6, TNFα, and CCL22, activates TGF-β signaling pathway, and promotes angiogenesis and epithelial–mesenchymal transition, thereby facilitating tumor progression." (PMID 35047494, 2021). "Therefore, the blockade of CD95L might be a significant approach to overcome the problem of chemo-resistance by diminishing the potential pro-inflammatory crosstalk role of TNF-α and TRAIL in the treatment of inflammation-driven tumor progression of PDAC." (PMID 34771621, 2021). "Consistent with the MC38 tumor model, RagD-deficient antigen-specific CD8+ T cells failed to suppress tumor growth, as well as a decrease in the proportions of IFN-γ+ TNF-α+ polyfunctional and IFN-γ-secreting, TNF-α-secreting and GZMB-secreting subpopulations from CD8+ TILs." (PMID 33883257, 2021). "Previous research with an experimental model showed that tumour factors, such as proteolysis-inducing factor (PIF), and pro-inflammatory cytokines, such as IL-6 and TNF-α, could jeopardise the placenta tissue, impairing the connection between the dams and foetus." (PMID 33916290, 2021). "However, the impacts of consistent proinflammatory stimulation by TNFα + IL-1β—reflecting chronic inflammatory processes that take place at the tumor site—were not investigated in TNBC." (PMID 34072893, 2021). "Besides CAFs, tumor-associated macrophages (TAMs), as myeloid derived suppressor cells, contribute to an immunosuppressive microenvironment and support tumor growth as they are a source of immunosuppressive cytokines (e.g., CCL17, CCL18 and CCL22) and tumor promoting growth factors (VEGF-A, TNF-α)." (PMID 34064974, 2021). "As PD-L1TC is induced by pro-inflammatory cytokines, such as IFNγ and TNFα produced by activated T cells, the reaction of tumour cells to the anti-tumour immune response of the host may not always be concordant among intratumoural locations." (PMID 31761900, 2020). "The decrease of serum TNF-α (tumor necrosis factor), IL-8 (interleukin-8), MMP-2 (matrix metalloprotein-2) and MMP-9 (matrix metalloprotein-9) of the treated C57BL/6 mice was correlated with the action pathway of RGDV-gemcitabine inhibiting the metastasis of the planted tumor towards lung." (PMID 32978501, 2020). "Tumour necrosis factor–related apoptosis‐inducing ligand (TRAIL) is a member of the tumour necrosis factor (TNF) superfamily which mainly induces apoptosis of tumour cells and transformed cell lines with no systemic toxicity, whereas they share high sequence homology with TNF and CD95L." (PMID 32827246, 2020). "Although the clinical usage of TNF-α has been limited by toxicity and side effects, using TNF-α alone or in combination with chemotherapy and radiotherapy as an adjuvant in cancer may offer great promise for tumor treatment." (PMID 32346605, 2020). "Additionally, we observed that the frequency of TI CD8+ T cells that secrete effector cytokines (IFN-γ and TNF-α) significantly increased upon TOX knockdown, suggesting that the anti-tumor function of TI CD8+ T cells could be restored upon TOX knockdown." (PMID 32111241, 2020). "Besides the reported TNFα, activated M1 but not M2 macrophages were previously found to produce family 18 chitinases that pose potent tumor-toxic acitivity." (PMID 32316245, 2020). "Clinical and experimental data indicate that, in the large majority of cancers, TAMs acquire an M2-like tumor-promoting phenotype characterized by high levels of immunosuppressive markers (e.g., ARG1, MMR1, IL10), as opposed to low levels of inflammatory cytokines (e.g., IL-12, IL1β, TNFα)." (PMID 32823961, 2020).
tumor (continued). "In addition, mRNA expression of IFN-γ and TNF-α in the heart tissue increased significantly in the anti-PD-1-treated tumor group compared to the anti-PD-1-treated non-tumor group." (PMID 32244307, 2020). "Moreover, in a MC38 tumor model, response to anti-PD-1 was dependent on intratumoral cDC1 production of CXCL9 and subsequent signaling through CXCR3 on T cells, which promoted proliferation and production of IFNγ, TNFα, and Granzyme B." (PMID 33584701, 2020). "Depletion of TNFα did not alter the anti-tumor effect of PD-L1 CAR haNKs." (PMID 32633234, 2020). "Importantly, this leads to the recruitment of T cells and production of IFN-γ, IL-2, and TNF-α, which leads to tumor cell kill, but not necessarily through tumor specific mechanisms." (PMID 32858811, 2020). "However, the extract treatment in animals without a tumor showed a high level of seric TNF-α concentration (306.9 ± 17.93 pg/mL) compared to normal animals." (PMID 33138062, 2020). "Since it mainly displays tumor suppressive properties, it is not surprising that low levels of its expression are detected in the stroma of many solid tumors, including PC, and its production is suppressed at a transcriptional level by TNF-α." (PMID 32012917, 2020). "For instance, recent data indicate that dysbiosis impairs TNF production, expression of endothelial adhesion molecules and the consequent recruitment of protective IFN-γ-producing CD8 + T cells into the tumour microenvironment, which could partially support our findings." (PMID 32499569, 2020). "Notably, TNFα, through the activation of the NF-κB pathway, also up-regulates CSN2, which, by blocking the ubiquitination of the transcription factor SNAIL, promotes tumor invasiveness." (PMID 33324403, 2020). "Moreover, inflammation may be an agent in the process, and various inflammatory cytokines such as IL-6, IL-8, TNF-α, and PGE have impacts on the tumor microenvironment, which could aid tumor progression." (PMID 33003438, 2020). "Furthermore, IL-7, a key cytokine produced by immune cells in the tumour context, is able to increase RANKL and other inflammatory cytokines such as TNFα in osteoblasts and bone marrow stromal cells, thus increasing osteoclastogenesis and fuelling bone degradation in the metastatic context." (PMID 32527062, 2020). "Indeed, continual or prolonged exposure to the tumor antigen can induce functional exhaustion of the T cells and tumor-infiltrating TCR-engineered T cells can progressively lose the ability to produce IFNγ and TNFα." (PMID 33425916, 2020). "Importantly, GSEA analysis of RNA-seq data demonstrated that knockdown circPRRC2A correlates significantly with downregulation of EMT target genes, also confirmed that circPRRC2A is positively correlated with tumor angiogenesis and negatively correlated with the KRAS and TNF-α pathways." (PMID 32292503, 2020). "In addition, NK cells produce proinflammatory cytokines like interferon gamma (IFNγ) and tumor necrosis factor alpha (TNF) upon encountering a target cell, thereby inducing direct as well as indirect anti-tumor effects like the activation and differentiation of naïve T cells." (PMID 33123121, 2020). "Notably, we have recently demonstrated that tumor-derived PGE2 drives the nuclear accumulation of p50 NF-κB in CD11b+Ly6G-Ly6Chigh M-MDSC, diverting their response to IFNγ towards NO-mediated immunosuppression and reducing TNFα expression." (PMID 32962159, 2020). "No major differences were observed within the CD4+ tumor-reactive TILs, which appeared to be primarily characterized by tumor necrosis factor (TNF) production only, and a smaller population releasing both IFNγ and TNF." (PMID 33198174, 2020). "In contrast, IL-17A and TNF secretion by TCRγδCD8− T cells is not affected by Treg depletion and could counteract the CD8αβ T cell-mediated anti-tumor response." (PMID 32185408, 2020).